IL10 (interleukin 10)
Diseases named in the same sentence as IL10 in open-access papers (continued):
Sharing a sentence is not in itself a finding about the gene and the disease.
colorectal cancer (continued). "Augmentation of CD4+ T cells, CD8+ T cells and CD49b+ NK cells, as well as increased expressions of IFNg, IL10, CXCR4, and reduced expressions of IL17, STAT3 screened from gene and protein levels, jointly create a microenvironment conducive to inhibit the progress of colorectal cancer." (PMID 37143538, 2023). "Furthermore, the decreased infiltration of CD8+ T cells together with down-regulation of IL10 and up-regulation of IL17, STAT3 in the intestine, create an intestinal microenvironment prone to inflammation and the occurrence and development of colorectal cancer." (PMID 37143538, 2023). "One colorectal cancer patient with long-term anti-PD-1 monotherapy developed cytokine release syndrome (CRS) 5 days after receiving the Pfizer-BioNTech mRNA COVID-19 vaccine with evidence of increased inflammatory markers and elevated cytokine levels (IFN-γ, IL-2R, IL-18, IL-16, and IL-10)." (PMID 36033814, 2022). "Therefore, examining the relationship between this miRNA and IL-10 in CAC could be an interesting topic for future studies and may be useful in elucidating the mechanism of IBD progression to colorectal cancer." (PMID 35410210, 2022). "Interestingly, Faecalibacterium prausnitzii and its supernatant could also regulate the expression of IL-10 and TNF-α, and then inhibit load of colorectal cancer." (PMID 32272885, 2020). "Furthermore, we are currently designing a targeted delivery system for this stable IL-10 isoform by conjugating it to tumor-specific antibodies (e.g., anti-EGFR) to improve intratumoral accumulation and therapeutic efficacy in preclinical models of colorectal carcinoma." (PMID 40149345, 2025). "Despite these bacteria being widely known to constrain the inflammatory response, the opposite effect may occur in mice presenting colorectal cancer, in gnotobiotic animals harboring a specific pathogen or in certain gene deletions, such as in mice not presenting the gene coding for IL-10." (PMID 36838425, 2023). "While no anti-human IL-10 antibody has been approved for cancer treatment, the production of IL-17A and adenosine could be targeted in tumors that are highly infiltrated by pro-tumor γδ T cells, such as breast and colorectal cancer." (PMID 33042132, 2020). "Others have reported that absence of IL-10 to increase the risk of acute lymphoblastic leukaemia occurrence (ALL), and the polymorphisms of IL-10 may be associated with an increasing risk of colorectal cancer." (PMID 26528857, 2015).
gastric cancer (154 papers, 2010 to 2026). A primary or metastatic malignant neoplasm involving the stomach. "High levels of IL-10 in gastric cancer patients are associated with poor prognosis since it supports a tolerogenic environment for the tumor to evade immune surveillance." (PMID 40309351, 2025). "TCGA gastric cancer data confirmed a positive correlation between Foxp3 and IL-10, TGF-β1 expression, and linked these molecules to poor prognosis in gastric cancer patients." (PMID 41438510, 2025). "Asian populations have polymorphisms of the interleukin genes (IL-17 and IL-10) that increase the risk of gastric cancer, due to their interaction with H. pylori and the habit of smoking." (PMID 38301538, 2024). "The correlation between gastric cancer and T/C single nucleotide polymorphism (SNP) of interleukin-10 (IL-10) promoter−819(rs1800871)was opaque and remained to be determined." (PMID 38365575, 2024). "More models are expected to explore the relationship between IL-10 819 promoter polymorphism and gastric cancer." (PMID 38365575, 2024). "Subgroup analysis showed that in the allele genetic model of IL-10 819 C/T polymorphism, the mutant allele was significantly associated with the increased risk of gastric cancer among Asians, Latinos and Caucasians." (PMID 38365575, 2024). "As a result of these transitions, decreased IL-10 production leads to severe gastric inflammation and a consequently higher risk of developing gastric carcinoma in H.-pylori-positive patients." (PMID 35884067, 2022). "In gastric cancer patients, increased mRNA levels of IL10 were also associated with worse survival in multivariate analysis." (PMID 32100077, 2020). "We analyzed the Interleukin-10 (IL-10) single nucleotide polymorphism (SNP) and IgG subclass responses to the bacteria in patients with early gastric cancer and recurrent gastric cancer." (PMID 30792753, 2019). "Some reports have indicated that IL-10 response and T helper polarity were associated with gastric cancer development." (PMID 30792753, 2019). "A series of studies have evaluated the association between -592A>C and -819T>C polymorphisms in the promoter regions of Interleukin-10 (IL-10) and gastric cancer (GC) risk." (PMID 30624524, 2019). "Some studies have illustrated that the IL-10 rs1800896 polymorphism was correlated with enhanced risk of nasopharyngeal carcinoma and gastric cancer, diabetic nephropathy, and non-Hodgkin's lymphoma." (PMID 28410223, 2017). "The C allele of the present IL-10 819T/C polymorphism was associated with increased risk for gastric cancer." (PMID 28576445, 2017). "Our findings provided evidence for a causal role of genetically elevated IL-10 in the development of gastric cancer, especially in East Asians and for intestinal type gastric cancer." (PMID 26886630, 2016). "The most noteworthy finding of this study was that genetically elevated circulating IL-10 was significantly associated with an increased risk of gastric cancer by employing -1082A>G as an instrument." (PMID 26886630, 2016). "We found that, in patients with gastric carcinoma, peripheral levels of IL-17 were correlated only with IL-12 concentrations, whereas IL-23 levels were significantly associated with IL-10 values." (PMID 27869179, 2016). "In the present study, the higher MMP activity exerted by IL-10-stimulated macrophages seems to be associated with the enhancement of gastric cancer cell invasion." (PMID 26043921, 2015). "Polymorphisms in IL-1β, TNF-γ, and IL-10 are host-dependent genetic factors which also contribute to the multifactorial origin of gastric cancer." (PMID 26379360, 2015). "We found that systemic levels of only selected ILs and/or IL ratios (IL-6, IL-8, IL-6/IL-8 and IL-6/IL-10) showed potential as diagnostic markers for the detection/discrimination of gastric cancer (with a sensitivity and specificity of approximately 54–72%)." (PMID 26486258, 2015).
gastric cancer (continued). "It is natural that high-quality studies should be designed in the future so as to accurately explore the real associations between IL-10-592 AA genotype and gastric cancer susceptibility among different ethnicities." (PMID 22859944, 2012). "Study Characteristics of genotypes in gastric cancer cases and controls in the analysis of Interleukin-10 -592 Promoter Genetic Polymorphism." (PMID 22859944, 2012). "Those 11 studies seemed appropriate to the meta-analysis of the associations with gastric cancer regarding IL-10-819 T/C SNP." (PMID 22436502, 2012). "Multiple logistic regression models were used to detect the effects of IL10 polymorphisms, H. pylori infection, and smoking on the risk of gastric cancer, which was stratified by the histological type of gastric cancer." (PMID 22235320, 2012). "Accordingly, the aim of our meta-analysis was to shed more light, using the most appropriate genetic model, on the role of IL-10-592 A/C SNP in the risk of developing gastric cancer and to identify possible sources of heterogeneity among the eligible studies." (PMID 22859944, 2012). "Accordingly, the aim of our meta-analysis was to shed more light, using the most appropriate genetic model, on the role of IL-10-819 C/T SNP in the risk of developing gastric cancer and to identify possible sources of heterogeneity among the eligible studies." (PMID 22436502, 2012). "The association between current smoking and an increased risk of gastric cancer was stronger amongst IL10-1082G carriers and IL10-592C carriers." (PMID 22235320, 2012). "We aimed to explore the role of T/C SNP of IL-10 -819 in the susceptibility to gastric cancer through a systematic review and meta-analysis." (PMID 22436502, 2012). "Individuals carrying genotypes associated with increased pro-inflammatory cytokine production and/or decreased anti-inflammatory cytokine IL-10 production reportedly have increased risk of gastric cancer." (PMID 22526791, 2012). "Certainly, the real association between H pylori infection and IL-10-819 TT genotype and gastric cancer susceptibility should be further meticulously investigated in the future." (PMID 22436502, 2012). "Certainly, the real association between H pylori infection and IL-10-592 AA genotype and gastric cancer susceptibility should be further meticulously investigated in the future." (PMID 22859944, 2012). "Potential functional allele T/C single nucleotide polymorphism (SNP) of Interleukin 10 (IL-10) promoter -819 (rs1800871) has been implicated in gastric cancer risk." (PMID 22436502, 2012). "We aimed to explore the role of IL-10 -592 A/C SNP in the susceptibility to gastric cancer through a systematic review and meta-analysis." (PMID 22859944, 2012). "Although many studies have investigated the roles of IL10 promoter polymorphisms and the risk of gastric cancer, the findings remain inconclusive, possibly due to differences in study design and/or ethnic differences in the populations studied." (PMID 22235320, 2012). "A number of studies have reported an association between IL10 promoter polymorphisms (-1082G/-819C/-592C) and the risk of gastric cancer, but these findings have been inconsistent." (PMID 22235320, 2012). "It has been reported that these variants of IL10 are associated with increased IL10 production and an elevated risk of gastric cancer." (PMID 22235320, 2012). "Those 17 studies were preliminarily appropriate to the meta-analysis of the associations with gastric cancer regarding IL-10-592 A/C SNP." (PMID 22859944, 2012). "IL-10 -819 TT genotype is associated with the overall reduced gastric cancer risk among Asians and even apparently observed among high quality subgroup Asians." (PMID 22436502, 2012). "Especially, inflammatory cytokine gene polymorphisms (IL-1 gene cluster, TNF-α, IL-10, and IL-8) have been reported to be correlated with gastric cancer." (PMID 22189161, 2011).
gastric cancer (continued). "In a study of gastric cancer patients from Mexico, the IL10-592 CC genotype was associated with an OR of 2.2 (95% CI 1.0–4.6) for intestinal-type gastric cancer." (PMID 19888225, 2010). "Therefore, we performed this meta-analysis to better analyze the correlation between IL-10 gene polymorphisms and gastric cancer." (PMID 38365575, 2024). "Generally speaking, our meta-analysis study in different populations confirmed that interleukin-10-819 promoter polymorphism could be used as a genetic biomarker of gastric cancer." (PMID 38365575, 2024). "In addition, in the future, we can investigate the role of IL-10 819 single nucleotide polymorphisms on in the prognosis of gastric cancer at different stages more accurately by further elaborate studies with cancer gene mutation screening kits." (PMID 38365575, 2024). "Additionally, IL-10 released by Bregs at hypomethylation has been associated with poor prognosis and worse OS in patients with gastric cancer." (PMID 39840050, 2024). "IL-10 has been linked to many types of cancers such as gastric cancer (Ref." (PMID 38186186, 2024). "In Colombia, it has been observed that the presence of the 1082 (A/G) point mutation in the IL-10 gene (79%), together with another mutation in position 511 of the IL-1β gene (72%) and the Th1 immune response, increase the risk for gastric cancer in human populations." (PMID 39061325, 2024). "Moreover, Wang and co-authors reported that the IL-10 rs1800871, rs1800872, and rs1800896 polymorphisms were significantly associated with the risk of gastric cancer in Asians under two models: dominant and additive." (PMID 36009467, 2022). "In this case, our study indicated that the IL-10 polymorphisms (rs1800871, rs1800872, rs1800896) could serve as genetic biomarkers of gastric cancer in Asians." (PMID 36009467, 2022). "Therefore, some studies raise the possibility of IL-10 rs1800872 and IL-10 rs1800896 polymorphisms as genetic biomarkers of gastric cancer." (PMID 35207552, 2022). "An increase in the ratio of IL6/IL10 has been associated with gastric cancer prognosis." (PMID 32256476, 2020). "Dominance of T helper 2 (Th2) immunity controlled by IL-10 cytokine may be associated with H. pylori-associated gastric cancer recurrence." (PMID 30792753, 2019). "There are three frequently detected SNPs of IL-10 promoter gene, at position-1082 A/G and − 819 C/T SNPs in its proximal promoter region and at position − 592 A/C SNP in its 5′-flanking region, which are associate with IL-10 production and development of gastric cancer." (PMID 30792753, 2019). "Moreover, extending previous understandings of the close relationship between IL-10 genetic variants and gastric cancer, we further pinpointed a remarkable contribution of -1082A>G to intestinal type gastric cancer." (PMID 26886630, 2016). "Recently it has been reported that smoking suppresses regulatory B cell and inhibits the production of interleukin 10; both events may increase the risk of gastric cancer." (PMID 26839536, 2016). "Since the 95% CIs of both predicted estimates excluded the null hypothesis value of 1, it is safe to reject the null hypothesis at a 5% significance level, and suggested a potentially causal association of circulating IL-10 level with gastric cancer." (PMID 26886630, 2016). "Similarly, A/G polymorphisms at −1082 in IL-10 have been reported in association with intestinal-type of gastric cancer at cardia location." (PMID 26379360, 2015). "The IL10 gene encodes a cytokine that plays a role in immunoregulation and inflammation, and has been previously linked to several cancers, including osteosarcoma, cervical cancer, and gastric cancer." (PMID 24159917, 2013). "In conclusion, IL-10-592 AA genotype may seem to be more protective from overall gastric cancer susceptibility among Asians and may also seem to be more protective from overall gastric cancer susceptibility in persons infected with H. pylori." (PMID 22859944, 2012).
gastric cancer (continued). "However, the roles of IL10 and its polymorphisms in the pathogenesis of gastric cancer require further investigation." (PMID 22235320, 2012). "In conclusion, IL-10-819 TT genotype may seem to be more protective from overall gastric cancer susceptibility among Asians and even more protective in high quality subgroup Asians." (PMID 22436502, 2012). "In accord with our findings, recent meta-analyses suggested that Asian carriers of the promoter polymorphisms of IL10 may be associated with an increased risk of gastric cancer." (PMID 22235320, 2012). "Whether IL-10 -819 TT genotype may be protective from gastric cancer susceptibility in persons infected with H. pylori or in diffuse-subtype cancer needs further exploring in the future well-designed high quality studies among different ethnicity populations." (PMID 22436502, 2012). "Therefore, it should be advocated that more rigorous high-quality studies should be designed in the future so as to accurately explore the real associations between IL-10-819 TT genotype and gastric cancer susceptibility among different ethnicities." (PMID 22436502, 2012). "In recent years, a number of studies have shown that the presence of the IL-10 819 C allele is associated with an increased risk of gastric cancer, and further studies have found that the IL-10 819 C allele is associated with an increased risk of gastric cancer in patients with HP infection." (PMID 38365575, 2024). "Gastric cancer (GC)-derived exosomes cause macrophages to polarize towards the M2 type and express PD-1, leading to increased production of IL-10 and accelerated tumor growth by preventing T cell activation." (PMID 38195554, 2024). "On the other hand, other evidence concluded that some IL-10 variants are associated with higher expression of IL-10 and consequently, an elevated risk for cancer development of multiple myeloma, cervical cancer and gastric cancer in patients harbouring a particular IL-10 variant (Refs 216–218)." (PMID 38186186, 2024). "Therefore, Th1/Th2 immunity balance controlled by IL-10 may be associated with the risk of H. pylori-associated gastric cancer recurrence." (PMID 30792753, 2019). "Thus, IL-10-819 TT genotype may seem to be more protective from overall gastric cancer susceptibility among Asians." (PMID 22436502, 2012). "IL-10-592 AA genotype is associated with the reduced risk of developing gastric cancer among Asians and even apparently observed among Asians high quality subgroup, suggesting IL-10-592 AA genotype may seem to be more protective from overall gastric cancer in Asian populations." (PMID 22859944, 2012). "Thus, IL-10-592 AA genotype may seem to be more protective from overall gastric cancer susceptibility among Asians." (PMID 22859944, 2012). "In gastric cancer, Foxp3, IL-10, and TGF-β1 create a tightly coordinated immunosuppressive synergistic network." (PMID 41438510, 2025). "In gastric cancer, the expression patterns of IL-10 and TGF-β1 family molecules consistently differed between tumor and normal tissues, as observed in both the TCGA single cohort and the TCGA + GTEx integrated cohort analyses." (PMID 41438510, 2025). "Taken together, it is likely that IL-10 is involved in lidocaine-modulated mechanisms against gastric cancer." (PMID 40244064, 2025). "In‐vivo immunomodulatory effect on gastric cancer rats: Promotes splenocyte proliferation and improves anti‐inflammatory cytokines (IL‐2, IL‐4, and IL‐10) secretion." (PMID 41211514, 2025). "Targeting IL-10+ TAMs can transform the immune-evasive microenvironment, presenting a potential therapeutic approach for gastric cancer." (PMID 40507854, 2025). "In gastric cancer tissues, IL-10 and TGF-β1-related factors exhibit overlapping high expression intervals, as shown by the synchronous expansion of high expression regions in the red violin plot." (PMID 41438510, 2025).